MYBL2 (MYB proto-oncogene like 2)
Diseases named in the same sentence as MYBL2 in open-access papers (continued):
Sharing a sentence is not in itself a finding about the gene and the disease.
cancer (174 papers, 2007 to 2026). A tumor composed of atypical neoplastic, often pleomorphic cells that invade other tissues. "While the MYB family of oncogenes is implicated in cancer, the role and regulatory mechanisms of its member, particularly MYB proto-oncogene like 2 (MYBL2), remain underexplored in HCC." (PMID 42065054, 2026). "The proliferative signature of cancer cells is known to be causally linked to expression of a core set of pro‐proliferative genes including MYBL2, BUB1, and polo‐like kinase 1 (PLK1)." (PMID 38538106, 2024). "One of the genes was MYBL2, encoding for a well-known transcription factor involved in the regulation of cell survival, proliferation, and differentiation in cancer tissues." (PMID 39518122, 2024). "Elevated expression of MYBL2 in various tumors is often associated with poor prognosis, rendering it a potential therapeutic target in cancer treatment." (PMID 38994352, 2024). "Recent literature had implied that MYBL2 showed high expression in various cancers and negatively associated with survival rates specific to tumors in patients." (PMID 38961953, 2024). "MYBL2, a key transcriptional factor associated with the cell cycle, plays a pivotal role in cancer progression." (PMID 37865750, 2023). "We then studied the association of MYBL2 and outcomes of men with mHSPC by profiling cancers from hormone‐naïve prostate gland specimens from 160 men in the CHAARTED trial." (PMID 36087093, 2022). "Meanwhile, survival analysis showed that hypermethylation of TFDP2, RBL1, and MYBL2 was associated with poor survival in most cancers." (PMID 35664326, 2022). "Survival analysis showed that hypermethylation of TFDP2, RBL1, and MYBL2 was associated with poor survival in most cancers." (PMID 35664326, 2022). "Along with previous reports, this study suggests that the MYBL2 gene polymorphism is complex, depending on cancer types." (PMID 34568071, 2021). "MYBL2 (encoding B-Myb), an oncogene with prognostic significance in several cancers, is highly expressed in most HGSOC cases; however, the clinical significance of B-Myb in this disease has not been well-characterized." (PMID 33747961, 2021). "Overexpression of MYBL2 is observed in several cancers and is associated with poor patient prognosis." (PMID 33660437, 2021). "MYBL2 was known to overexpress and associate with poor patient outcomes in many cancer entities; its expression positively correlated with CD4+ T cell infiltration but negatively correlated with B cell infiltration." (PMID 34489925, 2021). "Overexpression of MYBL2 has been observed in various types of cancer and has been linked to aggressive tumor growth and poor clinical prognosis 15-17." (PMID 33897882, 2021). "Among the activated transcriptional regulators identified, CENPA, FOXM1, and MYBL2 were linked to numerous cancer-specific enhancers." (PMID 32925947, 2020). "MYBL2 is associated with poor prognosis in numerous cancers and plays a vital role in the regulation of cell proliferation, cell survival, and differentiation." (PMID 32084007, 2020). "Having now identified these as key regulators in LUAD, we sought to determine if different enhancers are linked to FOXM1 and MYBL2 in the two cancer types." (PMID 32925947, 2020). "Of the transcriptional regulators activated in LUAD, CENPA, FOXM1, and MYBL2 were linked to the activation of hundreds of cancer-specific enhancers." (PMID 32925947, 2020). "The top activated transcriptional regulators were CENPA, FOXM1, TCF24, and MYBL2, which were linked to 875, 845, 843, and 840 cancer-specific enhancer probes, respectively." (PMID 32925947, 2020). "Overexpression of MYBL2 is associated with poor patient survival in various cancers patient including NSCLC." (PMID 31681566, 2019). "Kaplan-Meier survival curves show that higher expression of NEK2 and MYBL2 is also associated with worse clinical outcomes in various cancers." (PMID 28427185, 2017).
cancer (continued). "Because the rs619289 genotype impacts MYBL2 or A3B expression, we presumed that patients carrying the T allele would have greater mutation rates and poorer cancer outcomes." (PMID 28276478, 2017). "In fact, MYBL2 is overexpressed and associated with poor patient outcome in numerous cancer entities." (PMID 28640249, 2017). "For example, three members of the TF family MYB: MYB, MYBL1 and MYBL2, appear to be closely associated with cancer." (PMID 22041030, 2011). "Furthermore, MYBL2 regulates cell proliferation, survival and differentiation and its overexpression is associated with poor outcomes in different cancer types, including ACC." (PMID 39167619, 2024). "It is speculated that the proliferation of cancer cells caused by MYBL2 will lead to a relative decrease in PDC and other immune cells." (PMID 37686305, 2023). "Interestingly, this also identified a highly conserved member of the MYB family MYBL2, reported to be associated with poor patient outcome in various cancers, including AML50." (PMID 36333382, 2022). "Taken together, high MYBL2 is consistently associated with poorer patient prognosis in localized prostate cancer and mHSPC and leads to more aggressive cell lines and resistance to androgen deprivation and anti‐cancer therapies impacting cellular replication." (PMID 36087093, 2022). "MM-associated circular RNA MYB proto-oncogene like 2 (circ-MYBL2) has been shown to exert different roles in different cancers, while its role in PA is unknown." (PMID 35387554, 2022). "The finding that elevation of MYBL2 had a more consistent association with poorer mHSPC outcomes than lower KDM5D is consistent with MYBL2 being a transcription factor controlled by other factors that promote many of the hallmarks of cancer." (PMID 36087093, 2022). "Deregulation of Mybl2 expression is associated with cancer initiation and progression." (PMID 32419051, 2020). "Although this finding showed that the correlation between A3B and MYBL2 varied, it was apparent that the higher correlations were more prevalent in the cancer types that had a relatively lower median mutation load (P = 0.0055, Spearman’s r = −0.6588), i.e., A3B expression is regulated by B-Myb." (PMID 28276478, 2017). "Although the mutation load varied among the 33 cancer types in TCGA, we found that the median value for the C-to-T mutation load correlated positively with expression of A3B (Spearman’s r = 0.7706, P < 0.0001) and of MYBL2 (Spearman’s r = 0.5964, P = 0.0002)." (PMID 28276478, 2017). "Previous studies have implicated FOXM1 and MYBL2 overexpression in a range of different cancers." (PMID 25889361, 2015). "B-MYB (MYBL2), a mitotic regulator, could be implicated in breast tumorigenesis because it is detected in a wide variety of cancer cells and plays an essential role during cell cycle progression." (PMID 24639887, 2014). "Moreover, MYBL2 was also found to be enriched in high-grade ER-negative tumors and to associate with stem or progenitor function, and with cancer cell proliferation." (PMID 20126311, 2010). "In addition, the MYBL2 polymorphisms were reported to be associated with cancer." (PMID 34568071, 2021). "We employed multiple bioinformatics algorithms (GEPIA, TCGA, TIMER2.0) to analyze MYBL2 expression across different cancer types and in UCEC specifically." (PMID 40432915, 2025). "Nuclear EGFR increases cyclin D1, inducible nitric oxide synthase (iNOS), and MYBL2 (B-Myb), all of which are involved in cancer proliferation." (PMID 39948411, 2025). "MYBL2 is overexpressed in various cancers, and it regulates proliferation, progression, and immune infiltration in all cancers." (PMID 40236649, 2025). "In summary, this study demonstrated that MYBL2 was markedly overexpressed across various tumor types and was positively related to poor prognosis of patients with cancer." (PMID 40092688, 2025).
cancer (continued). "Remarkably, FOSL1 (in PAAD and LUAD) and MYBL2 (in PAAD and BRCA) consistently showed associations with worse survival across multiple cancer types." (PMID 39393173, 2024). "circMYBL2 is a circRNA originating from the gene MYBL2, which exhibits diverse roles across various cancers the cell cycle checkpoint gene MYBL2, exhibits diverse roles across various cancers." (PMID 38827325, 2024). "The DREAM complex is frequently affected in cancer, and the overexpression of MYBL2 has been observed in various aggressive subtypes of tumors and associated with poor clinical prognosis." (PMID 39113611, 2024). "MYBL2, a proto-oncogene belonging to the MYB family, plays a crucial role in tumor development and progression, being commonly upregulated in various cancer types and associated with poor patient outcomes." (PMID 39136009, 2024). "The human family of MYB transcription factors comprises MYB (c-MYB), MYBL2 (b-MYB), and MYBL1 (a-MYB), which are overexpressed in several cancers and are associated with cancer progression and resistance to anticancer drugs." (PMID 38835346, 2024). "Our research focused on the diversity within malignant epithelial cells in metastatic ovarian cancer at the individual cell level, revealing the significance of TOP2A and MYBL2 in this type of cancer." (PMID 39136009, 2024). "Substantial amounts of data document the association of c-MYB and MYBL2 in a variety of cancers, including breast cancers, compared to fewer studies describing the involvement of the MYBL1 gene in cancer processes." (PMID 38473786, 2024). "It has been shown that MYBL2 is a Wnt/β‐catenin target gene in different types of cancer‐xenograft models." (PMID 39167619, 2024). "As a central regulator in tumorigenesis, MYBL2 is involved in the proliferation, apoptosis, and differentiation of cancer cells." (PMID 38994352, 2024). "Further, while PRC1 displayed a greater module membership with the purple module, this gene was also found to be a downstream target of MYBL2 in other cancer cell lines." (PMID 37509213, 2023). "The increased MYBL2 gene expression in metastatic samples is in line with an observed overexpression and poor patient outcomes in numerous cancer entities." (PMID 37622176, 2023). "MYBL2 is an important physiological regulator of cell cycle progression and cell survival and promotes cancer initiation and/or progression when overexpressed." (PMID 37691636, 2023). "MYBL2 also plays a significant role in several types of cancers, such as colorectal cancer, prostate cancer, and breast cancer." (PMID 37865750, 2023). "The pan-cancer analysis indicated that MYBL2 was observed to be an overexpressed oncogene in multiple cancers." (PMID 37752167, 2023). "As a potential oncogene and biomarker in aggressive cancers, MYBL2 stimulates the malignant progression of tumors via cancer proliferation, drug resistance, and metastasis." (PMID 35557985, 2022). "Across cancers, we found that heterozygous loss events in XPC (2/5 tumor types), POLK (4/5), LIG4 (5/5), ATM (3/5), and TP53BP1 (3/5) were common in MYBL2 High tumors." (PMID 36358918, 2022). "mTOR pathway plays a critical role in tumorigenesis and cancer progression, and a potential correlation has been identified between MYBL2 and mTOR in Arabidopsis." (PMID 35557985, 2022). "We found that A549 cells exhibited higher MYBL2 expression compared to non-cancer cells (p-value < 0.05)." (PMID 36291764, 2022). "Various types of cancer reveal that the overexpression of MYBL2 results in aggressive tumors and a low survival rate." (PMID 35557985, 2022). "We observed that circ-MYBL2 was downregulated in PA and played tumor suppressive roles by inhibiting cancer cell proliferation." (PMID 35387554, 2022). "MYBL2 can promote cancer progression by promoting tumor cell proliferation and inducing treatment resistance and metastatic diffusion." (PMID 35664780, 2022).
cancer (continued). "It has been demonstrated that CENPA, MYBL2, and FOXM1 were linked to numerous cancer-specific enhancers, and their elevated expression levels were associated with a poor survival rate of NSCLC patients." (PMID 35721149, 2022). "Circ-MYBL2 is downregulated in PA and plays tumor suppressive roles by inhibiting cancer cell proliferation, migration, and invasion, possibly by downregulating miR-19a through methylation." (PMID 35387554, 2022). "Across cancers, we found that MYBL2 High tumors frequently gained copies of genes controlling DNA replication and repair." (PMID 36358918, 2022). "Our preliminary sequencing data revealed an inverse correlation between circ-MYBL2 and microRNA-19a (miR-19a), which is also a critical player in many cancers including PA." (PMID 35387554, 2022). "The in vivo study further proved the functions of the MALAT1/MYBL2/mTOR axis in cancer proliferation and glucose metabolism in PCa cells." (PMID 35557985, 2022). "We further analyzed the potential co-expression of EIF4EBP1 and either ETS1 or MYBL2 at the mRNA level in multiple different cancer types using datasets available in R2 AMC." (PMID 35228525, 2022). "MYBL2, a known oncogene in many cancers, functions as a master regulator of cell proliferation, apoptosis, cell cycle progression, drug resistance and metastasis." (PMID 35612714, 2022). "Taken together, our research suggests that MALAT1 controls cancer glucose metabolism and progression by upregulating MYBL2-mTOR axis." (PMID 35557985, 2022). "The activation of conduction factor CERK indirectly triggers dysregulation of the immune response, cancer cell proliferation, and metastasis by upregulating TF MYBL2 to overexpress." (PMID 35164166, 2022). "The study also provides evidence that MYBL2 is a promising target for cancer treatments and proposed a possible mechanism of HCC progression." (PMID 36494680, 2022). "FOXM1 and MYBL2 were significantly higher in tumors than in adjacent normal tissues in 70% (23/33) of cancers." (PMID 34489925, 2021). "MYBL2 promotes the malignant development of cancer via regulating various cellular processes including apoptosis, proliferation, differentiation, invasion, metastasis, and replication stress." (PMID 34568071, 2021). "In this study, we showed that the expression of MYBL2 was significantly upregulated in parallel with RRM2 in the cancer tissues of clinical CRC patients." (PMID 34234118, 2021). "Overexpression of B-Myb (encoded by MYBL2, a DREAM target gene) disrupts the DREAM complex in vitro and correlates with poor clinical outcomes in breast and other cancers." (PMID 33513914, 2021). "Among them, the expression of MYBL2 was significantly upregulated in parallel with RRM2 in the cancer tissues of all studied CRC cohorts." (PMID 34234118, 2021). "B-Myb (encoded by MYBL2) is a transcription factor oncoprotein that contributes to cell proliferation and poor clinical outcomes in cancer." (PMID 33747961, 2021). "Here we showed that CENPA, FOXM1, and MYBL2 are upregulated together, potentially leading to the activation of many cancer-specific enhancers in a subgroup of LUAD." (PMID 32925947, 2020). "When we compared our LUAD data with that of a similar analysis of BRCA, CENPA, FOXM1, and MYBL2 were also found to be activated, particularly in basal-subtype tumors, supporting the idea that these factors work together in certain cancer subtypes." (PMID 32925947, 2020). "As defective DNA repair results in distinct footprints observable in the cancer genome, we analyzed COSMIC mutational signature data for sequence-level evidence of error-prone DNA repair in MYBL2 High tumors." (PMID 33489883, 2020). "While IHC has been successfully used to detect phospho-specific MYBL2 in human carcinomas, a more feasible approach would be to employ IHC panels detecting MYBL2 and MYBL2-regulated targets such as FOXM1, CHK1, and RAD51." (PMID 33489883, 2020).
cancer (continued). "Both amplification of the 20q13 MYBL2 locus (encoding B-Myb) and over-expression of MMB target genes are associated with aberrant cell proliferation, cell cycle deregulation, and poor prognosis in many cancers including breast, liver, and ovarian." (PMID 29942794, 2018). "Analysis of TCGA database yielded similar results, supporting that MYBL2 and A3B are upregulated and putatively promote C-to-T transitions in multiple cancer types." (PMID 28276478, 2017). "Compared with the respective normal control, cancer types (18 of 21 cancers) showed that MYBL2 expression was significantly upregulated (P < 0.0001), implying its common role in cancers of almost every organ." (PMID 28276478, 2017). "ZMYND8 gene is localized at chromosomal region 20q13, which also contains candidate breast cancer oncogenes: MYBL2 (MYB proto-oncogene like 2), ZNF217 (zinc finger protein 217), and AURKA (aurora kinase A)." (PMID 28055972, 2017). "Meanwhile, MYBL2 amplification or overexpression has been observed in cancers such as myeloid leukemias (AML), hepatocellular carcinoma, breast cancer, and it is currently used as a marker for poor prognosis in colorectal carcinoma." (PMID 28784180, 2017). "Deregulation of MYBL2 expression can contribute significantly to cancer progression by promoting cancer cell proliferation, therapy resistance, metastatic spread and is correlated with poor patient outcome in several cancer entities." (PMID 28640249, 2017). "In this review, we summarize current knowledge on the physiological roles of MYBL2 and highlight the impact of its deregulation on cancer initiation and progression." (PMID 28640249, 2017). "Mybl2 have been related with infiltration of immune cells in several types of cancer." (PMID 38719901, 2024). "MYBL2 regulates cell cycle progression, survival, and differentiation in cancer cells." (PMID 36810084, 2023). "MYBL2 is a core regulator of cell cycle progression in the development of human cancers." (PMID 37538116, 2023). "We hypothesize that MYBL2′s downstream target gene could affect cancer cell proliferation and differentiation by promoting cell cycle progression." (PMID 37686305, 2023). "Importantly both CCNE1 and MYBL2 play important roles in promoting cell proliferation, an important cancer cell trait." (PMID 36803948, 2023). "A few studies have revealed that MYBL2 is correlated with immune infiltrates in cancer." (PMID 37865750, 2023). "In addition, it has been reported that the expression levels of UBE2C and MYBL2 show a strong positive correlation in a variety of cancers." (PMID 37840753, 2023). "Moreover, the results of GO analysis showed that MYBL2 influenced a variety of biological processes, particularly cell proliferation and cancer development." (PMID 35664780, 2022). "The overexpression of the oncogene MYBL2 (also known as B-Myb, MYB roto-oncogene like 2) has been confirmed to be associated with an increased rate of cell proliferation and can also become a valuable biomarker for poor cancer prognosis." (PMID 35310909, 2022). "Overexpression or amplification of MYBL2 had been widely reported in previous studies on cancer." (PMID 34568071, 2021). "On the other hand, deregulation of Mybl2 expression is involved in cancer initiation and progression, and high Mybl2 expression is significantly correlated with poor patient outcome in numerous cancers." (PMID 33504014, 2021).